BMI1 (BMI1 proto-oncogene, polycomb ring finger)
Diseases named in the same sentence as BMI1 in open-access papers (continued):
Sharing a sentence is not in itself a finding about the gene and the disease.
colon carcinoma (continued). "Here, we showed that ZNF277 also interacts with BMI1 in human colon cancer cells, although the functional significance of this interaction and whether ZNF277 is a component of the PRC1 complex in intestinal epithelial cells remains to be determined." (PMID 35015732, 2022). "Furthermore, the mRNA levels of c‐Myc, Bmi‐1, and Sox‐2, which are considered to be oncogenic in the colon cancer, were reduced by SIRT1 siRNA." (PMID 34826187, 2022). "BMI1 is an oncogene with elevated expression in colon cancer patients that is important for self-renewal of colon CSCs and promotes invasion and migration of colon cancer cells." (PMID 29416778, 2018). "Interestingly, recent evidence demonstrated that Wnt/β‐catenin signaling regulates Bmi1 expression in colon cancer cells." (PMID 28593132, 2017). "Using a colon cancer cell line HCT-116 and primary colon cancer cells, we have found that IL-1β can promote sphere-forming capacity concomitant with up-regulated expression of stemness markers Bmi1 and nestin in colon cancer cells, suggesting that IL-1β increases the self-renewal of colon CSCs." (PMID 23174018, 2012). "Therefore, it is conceivable to speculate the existence of more proliferative and active LGR5 and CD133 positive CSCs in human colon cancer than the existence of quiescent BMI1 positive cells." (PMID 31057717, 2019). "To determine whether any correlation exists between Hes1 expression and the expression of Bmi-1 in colon cancer biopsy samples, we obtained RNA from 28 normal samples and 28 colon cancer samples and analysed the expression levels of Hes1 and Bmi-1 through qRT-PCR." (PMID 26452029, 2015). "In addition, aberrant expression of Bmi-1 has been reported in human colon cancer and its expression levels correlate with clinical and pathological stages of colon malignancies, further assuring the oncogenic role of Bmi-1 in colon cancer." (PMID 23174018, 2012). "Thus, the parallel up-regulation of Zeb1 and Bmi1 by IL-1β suggests that IL-β-induced self-renewal of colon cancer cells may involve the Zeb1-Bmi1 pathway." (PMID 23174018, 2012). "Knocking down β-catenin also reduced BMI1 protein expression in FAC-treated FT194 cells, and it is interesting that β-catenin knockdown in colon cancer cells also resulted in reduced BMI1 expression." (PMID 31434871, 2019). "We also found increased expression of stem cell markers, including OCT4, Lin28, KLF, Bmi-1, CD44 and SOX2, in colon cancer cells upon treatment with BM-MSCs-derived exosomes." (PMID 30220706, 2018). "With these important targets of miR-15a, (BCL2, BMI1, YAP1 and DCLK1) in colon cancer having potential to promote colon cancer growth, we investigated the effects of miR-15a on cell proliferation." (PMID 29416778, 2018). "Several important colon cancer related genes, including well established targets of miR-15a, BCL2 and BMI1 as well as novel targets, YAP1 and DCLK1 contain binding sites for miR-15a in their 3’UTRs." (PMID 29416778, 2018). "Next, the clonality of Lgr5+ or Bmi1+ cell-derived small intestine tumors was examined using the FAP model, which provided similar results as with colon tumors." (PMID 28176811, 2017). "The constituents of PRC1 and PRC2 including BMI1 and EZH2, are often overexpressed in breast, prostate and colon cancer cells, and regulate oncogenic phenotypes." (PMID 27105531, 2016). "Our results provide functional and mechanistic links between Hes1 and Bmi-1/PTEN/Akt/GSK3β signaling in the development and progression of colon cancer." (PMID 26452029, 2015). "To validate, we selected colon-cancer cell-line HT29 (exhibits increased Wnt signaling) and expresses BMI1." (PMID 23671559, 2013). "Moreover, PAF1 knockdown decreased the expression levels of the genes such as LGR5, ID1, ID3, CD44v9, CD133, BMI1, RNF43, EPHB2, SOX9, and ASCL2, which are critical for inducing colon cancer stemness and its markers." (PMID 38182897, 2024).
colon carcinoma (continued). "IL-1β may foster CRC growth and invasion by stimulating colon cancer stem cell (CSC) self-renewal and upregulating stemness factor genes Bmi1 and Nestin." (PMID 38671854, 2024). "MIR34A expression resulted in downregulation of the stemness factors BMI1 proto-oncogene polycomb ring finger (BMI1), CD44, CD133, olfactomedin 4 (OLFM4), and MYC proto-oncogene bHLH transcription factor (MYC) in a colon cancer cell line, clearly connecting this axis to stemness." (PMID 38009093, 2023). "To determine whether ZNF277 interacts physically with BMI1 in humans, we performed co-IP using protein extracts from SNUC4 human colon cancer cells; these experiments showed robust ZNF277 and BMI1 protein expression." (PMID 35015732, 2022). "In addition, we found increased expression of stem cell markers, including OCT4, Lin28, KLF, Bmi-1, CD44 and SOX2, in colon cancer cells upon treatment of BM-MSC-derived exosomes." (PMID 30220706, 2018). "When 100 pmol of control miRNA, miR-15a or Mimic-1 was added to colon cancer cells growing in 2 ml regular growth medium (50 nM), we found that protein expression of target genes YAP1, and BMI1 was reduced in cells three days after treatment with Mimic-1, but not in cells treated with miR-15a." (PMID 29416778, 2018). "In conclusion, high mRNA expressions for LGR5, BMI1, TET1 and TET2 in the CD133 and EpCAM positive CSCs may be a useful criterion for better identification of the cells involved in colon cancer in order to specify therapeutic targets against this type of cancer." (PMID 31057717, 2019). "However, recent studies by others have shown that NANK, a human colon tumor cell line with a high level of Bmi-1 expression but negative for CD133, CD44, Oct4, and Nanog, is capable of initiating tumors in mice." (PMID 23174018, 2012). "Silencing of Bmi1 in many other cells such as PC3 and DU145 prostate, MDA-MB 468 breast and RKO colon cancer cell lines had by itself a strong toxic effect (data not shown) that hindered testing sensitization to the drug." (PMID 19956605, 2009). "Similarly, suppression of endogenous TMPRSS4 reduced ALDH activity in HT-29 and HCT-116 colon cancer cells, and this was accompanied by downregulation of SLUG, TWIST1, and SOX2, but not BMI1 or CD133." (PMID 34809669, 2021). "In addition, in another public transcript data set (GSE76342) for the colon cancer cell line LoVo with or without metformin treatment, we found that metformin inhibited expression of the CSC markers Lgr5, ASCL2, EPHB3, OLFM4, BMI1, Lrig1, TERT, CD44, and CD133." (PMID 32911743, 2020).
leukemia (46 papers, 2006 to 2025). A malignant (clonal) hematologic disorder, involving hematopoietic stem cells and characterized by the presence of primitive or atypical myeloid or lymphoid cells in the bone marrow and the blood. "BMI1 has also been implicated in tumorigenesis, primarily in leukemias, and in several human cancers including HNSCC." (PMID 24612587, 2014). "Deregulation of BMI-1, such as in gene amplification and protein overexpression, has been linked to the tumorigenesis of leukemia and solid tumors like oligodendroglial tumors and prostate, breast, and colorectal cancers." (PMID 23559850, 2013). "does not necessarily causes leukaemogenesis, but mass data show that BMI1 is crucial in leukaemic reprogramming collaborated with other partner contributing to the development of leukaemia, such as MLL-AF9, BCR-ABL, PLZF-RARA and even Runx1 mutation in clonal-disordered cells." (PMID 24571310, 2014). "In leukemia, hypoxia-induced BMI1 activation promotes chemoresistance in leukemia stem cells by activating the PI3K/Akt pathway and inducing EMT." (PMID 40623983, 2025). "For example, BMI1 is overexpressed in various types of leukemia, which is related to the signature BMI1_DN_MEL18_DN.V1_DN." (PMID 40221401, 2025). "Studies have confirmed that the occurrence and development of various human tumors, such as leukemia, breast cancer, gastric cancer, lung cancer, bladder cancer, colorectal cancer and esophageal cancer, are related to abnormal expression of the BMI1 gene." (PMID 38779660, 2024). "The overexpression of Bmi1 in WT leukemic cells results in the development of a more aggressive leukemia that results in ~40% of the transplanted mice dying much faster than controls." (PMID 35650206, 2022). "BMI1 has been studied extensively in the context of leukemia, and was one of the first PcG proteins identified as oncogenic in hematological diseases." (PMID 34617019, 2021). "The BMI1 gene plays an important role in regulating the proliferation of normal cells and leukemia stem cells." (PMID 33659248, 2021). "Ectopic expression of BMI1 gives rise to B- and T-cell lymphomas, and deletion of BMI1 delays primary leukemia and blocks secondary leukemia." (PMID 34617019, 2021). "Correspondingly, the transcript-level expressions of stem cell-associated genes, including OCT4, KLF4, BMI1, NANOG and SOX2, were significantly increased in leukemia cells upon treatment with exosomes from BM-MSCs." (PMID 33789743, 2021). "c-Myc mediates BMI1 gene transcription to ensure BMI1 availability during oncogenesis for leukemia, neuroblastoma, and nasopharyngeal carcinoma." (PMID 32183428, 2020). "Polycomb group gene B-cell-specific Moloney murine leukemia virus integration site-1 (BMI1) is crucial to regulate the proliferative activity of normal and leukemia stem cells." (PMID 32436945, 2020). "One of the predicted putative targets of miR-128b is BMI1, a transcriptional factor which is important in hematopoietic stem cells and leukemia stem-cell self-renewal." (PMID 31727091, 2019). "In leukemia stem cells, down-regulation of miR-203 increases proliferation and self-renewal capacities via targeting of survivin and Bmi-1." (PMID 29228583, 2017). "Several signaling pathways such as Bmi-1, Notch, Wnt/β-catenin, Sonic hedgehog and NF-kB have been implicated in CSC/LIC self-renewal and survival in leukemia and other solid cancers." (PMID 28920078, 2017). "The higher expression of BMI-1 in the Kasumi cell line compared to KG-1a confirms the role of BMI-1 in cell proliferation in leukemia and the possibility to use BMI-1 as target for new strategies against AML." (PMID 27506934, 2016). "In our study, we expanded knowledge on miR-203 activities via characterization of its two key targets, survivin and Bmi-1, which play essential roles in leukemia." (PMID 26847520, 2016). "miR-203 has been proposed as a tumor suppressor in leukemia stem cells because it targets various oncogenes such as Src, survivin and Bmi-1." (PMID 27517632, 2016).
leukemia (continued). "Meanwhile, Pten, as a tumour suppresser gene and contributing to leukaemia development, inhibits BMI1 promoting stem cell self-renewal and tumourigenesis, indicating that PTEN rescues the phenotypes by the overexpression of BMI1." (PMID 24571310, 2014). "It has been shown that BMI-1 overexpression occurs in a variety of cancers including several types of leukemias and lymphomas." (PMID 23067006, 2012). "A recent report similarly demonstrated that co-transduction of BMI1 and Bcr-Abl oncogenes in HSCs induced leukemia, in which ectopic expression of BMI1 probably functioned as the additional hit, in NOD/SCID mice." (PMID 22745659, 2012). "In several tumour types, such as leukaemia and hepatocellular carcinoma, BMI1 overexpression is indeed correlated with reduced survival." (PMID 19099573, 2008). "Parallel to these normal organ systems, Bmi-1 can also play an integral role in the malignant transformation of the HOX A9/MEIS – induced murine leukemia model as well as in tumors of neural origin." (PMID 17140455, 2006). "BMI1, a member of polycomb-group proteins, is directly involved in the regulation of cell growth and proliferation and is required for the self-renewal of adult stem cells and leukemia stem cells." (PMID 38779660, 2024). "One of the key regulators of self-renewal in several types of cancer including leukemia is Bmi1." (PMID 33297302, 2020). "In contrast, repression of Bmi1 impaired self-renewal and induced apoptosis in leukemia stem cells." (PMID 29685144, 2018). "The results indicated that Bmi-1 expression was related to leukemia relapse; thus, we hypothesized that Bmi-1 could act as a biomarker for predicting leukemia relapse." (PMID 28122538, 2017). "We next investigated if overexpressed BMI-1 protects leukemia cells from PTC596-induced apoptosis." (PMID 28211885, 2017). "Deletion of BMI1 inhibits self-renewal of tumor stem cells and prevents leukemia recurrence." (PMID 23431463, 2013). "In addition, we examined the cancer-related genes located within 30 kb of the FV and RV integration sites because all the RV insertion sites in gene therapy-related leukemia were shown within gene or within 30 kb of TSS of LMO-2 or BMI1." (PMID 23990961, 2013). "Moreover, we suggest that the miR-203/survivin/Bmi-1 axis could provide a potential therapeutic target for leukemia treatment." (PMID 26847520, 2016). "In leukemia, miR-203 expression is diminished in CD34 + AML cells, directly targeting survivin and Bmi-1 to impede the self-renewal ability of leukemia stem cells." (PMID 40710326, 2025). "Our group has demonstrated that BMI1 transforms and reprograms CML B-lymphoid progenitors into self-renewing, leukemia initiating cells." (PMID 35650206, 2022). "Co-expression of BMI1 and BCR-ABL in human cord blood CD34+ cells induces leukemia that can be propagated serially in immunodeficient mice with a bias towards lymphoid blast crisis." (PMID 35650206, 2022). "From these research databases, we selected four genes of interest, FLT-3, WT1, Bmi-1, and ABCG2, known as oncogenic and stem cell regulators that participate in leukemia initiation and progression." (PMID 26847520, 2016). "Finally, BCR::ABL+, BMI1+, and BCR::ABL+/BMI1+ CD34+ cells were transplanted into NOD/SCID mice to test for leukemia induction in vivo." (PMID 38201282, 2023). "In an in vitro leukemia model, two BMI1 inhibitors, PTC-209 and PRT-4165, down-regulating the expression of NOTCH1, HES1, and c-MYC, were able to block the leukemic cells growth, suggesting that the BMI1 inhibitors can be good candidates against leukemia." (PMID 30574454, 2018). "Other studies show BMI1 copy number in NSCLC is unchanged, whereas chromosomal aberrations that may result in up-regulation of BMI1 were shown in leukemia." (PMID 28445986, 2017).
leukemia (continued). "Therefore, we analyzed the expression of the HOXA gene cluster, its co-factor MEIS1 and BMI1, all known to be deregulated in CALM/AF10-positive leukemias." (PMID 27588395, 2016). "The ability of retroviral vector integration to initiate clonal expansion resulting in patient leukaemias with insertions at a subset of integration hotspots (LMO2, BMI1, CCND2) in gene therapy trials indicates the translational relevance of these observations." (PMID 27097319, 2016). "Both miR-27a and miR-128b might target BMI1, a transcription factor of the polycomb-group gene necessary for hematopoietic stem cell (HSC) and leukemia stem-cell self-renewal." (PMID 23431463, 2013). "In humans, BMI-1 is highly expressed in purified HSCs, and its expression declines with differentiation, and it plays an essential role in regulating adult, self-renewing HSPC and leukemia stem cells." (PMID 23067006, 2012). "Bmi-1 is the target gene of SALL4 in human hematopoietic as well as leukemic cells and is down-regulated if SALL4 is knocked down by the siRNA in the HL-60 leukemia cell line." (PMID 20936121, 2011). "BCR::ABL+, as well as BMI1+ cells alone, were not able to introduce leukemia within 25 weeks post-transplantation, whereas 50% of BCR::ABL+/BMI1+ mice succumbed to leukemia within weeks." (PMID 38201282, 2023). "While the role of ARRB1 in regulating Bmi-1 in leukemia has not been established, there is evidence that ARRB1 is essential for maintaining Bmi1 driven self-renewal in bladder cancer." (PMID 33297302, 2020).
melanoma (44 papers, 2008 to 2025). A malignant, usually aggressive tumor composed of atypical, neoplastic melanocytes. "It has been shown that in melanoma and nasopharyngeal cancer, the inhibition of BMI-1 expression caused the inhibition of epithelial—mesenchymal transition of these cells." (PMID 36497428, 2022). "Here, we show that SSX2, a germline-specific protein ectopically expressed in melanoma and other types of human cancers, is a chromatin-associated protein that antagonizes BMI1 and EZH2 PcG body formation and derepresses PcG target genes." (PMID 25249625, 2014). "Conversely, decreased expression of PcG proteins has also been observed in tumor samples, such as the downregulation of Bmi1 in melanoma, suggesting that loss of Polycomb complexes leads to activation of oncogenes." (PMID 25333635, 2014). "Apart from altered DNA-methylation patterns and microRNA deregulation, histone modifying enzymes such as histone deacetylases (HDAC) and polycomb repressive complex (PRC) members EZH2, JARID2, and BMI1, have been implicated in melanoma growth, epithelial-mesenchymal transition (EMT), and metastasis." (PMID 28978033, 2017). "In a recent study, Bmi1 induced an invasive signature that promoted metastasis and chemoresistance in melanoma." (PMID 36325671, 2022). "More advanced studies have used a soft 3D gel to promote cancer properties and upregulate stem cell markers (i.e., CD133, nestin, c‐kit, and BMI‐1) in melanoma cells, suggesting that a 3D soft environment promotes CD133‐expressing tumor‐repopulating cells." (PMID 33717837, 2021). "In melanoma, BMI1 expression was shown to be correlated with an invasive signature and to promote multiple aspects of melanoma metastasis, including anoikis, invasion, migration, and chemoresistance." (PMID 33523558, 2021). "The reduced expression of BMI1 inhibits epithelial-mesenchymal transition and spreading of melanoma cells." (PMID 34321511, 2021). "The overexpression of BMI1 in melanoma cells induced the invasive signature with concomitant nuclear accumulation of β-catenin." (PMID 32726929, 2020). "They observed a downregulation of miR‐200c in resistant melanoma tumors and cell lines, with a consequent upregulation of its targets, including BMI1, ZEB2, TUBB3, ABCG5 and MDR1." (PMID 30499222, 2019). "A recent study showed that Bmi1 induces an invasive signature that promotes metastasis and chemoresistance in melanoma." (PMID 29163356, 2017). "In melanoma cells, miR-203 was revealed to regulate melanoma invasive and proliferative abilities in part by targeting BMI1." (PMID 26388700, 2015). "Little is known about the role of PcG proteins in melanoma, but BMI1 and EZH2 are also deregulated and correlate with disease progression." (PMID 25249625, 2014). "In contrast to the results of our study, BMI1-mediated regression of p16INK4A has been reported to contribute to an increased incidence of metastasis in melanoma patients." (PMID 23046527, 2012). "Interestingly, our study showed that the reduction in Smo and Bmi1 expressions in CD133+ melanoma cell-injected mice, although significantly decreased compared with the control mice, was lower compared with other Shh-related genes." (PMID 36325671, 2022). "Therefore, the downregulation of Smo and Bmi1, strong mediators of metastasis and recurrence, by ornidazole treatment highlights the therapeutic efficacy of ornidazole in melanoma setting." (PMID 36325671, 2022). "Restoration of miR-200c expression or knockdown of Bmi-1 in resistant melanoma cells potentiates the effect of MAPK pathway inhibitory drugs and impairs the establishment of resistance, thus suggesting miR-200c as a potential therapeutic target for overcoming acquired BRAFi resistance." (PMID 32054078, 2020).